EGR1 (early growth response 1)
Diseases named in the same sentence as EGR1 in open-access papers (continued):
Sharing a sentence is not in itself a finding about the gene and the disease.
prostate carcinoma (continued). "EGR1 is known to function synergistically with NF-κB in upregulating IL-8 production in prostate cancer cells, and that its expression can be regulated by EGFR-integrin crosstalk." (PMID 29468142, 2018). "It is thus likely that, in prostate cancer patients, castration leads to upregulation of NF‐κB, EGR1 and TF expression in prostate epithelial cells." (PMID 29427323, 2018). "In a prostatecancer cell line (LN-CaP), Deopen recovers EGR1 which is believed to be the potentialtarget of gene therapy for prostate cancer (Baronet al., 2006)." (PMID 29069282, 2018). "The silencing of Egr-1 inhibits the proliferation of prostate cancer cell and growth in the transgenic adenocarcinoma prostate of mice." (PMID 30400241, 2018). "EGR1 is an important factor in prostate cancer, as it was shown to be overexpressed in malignant prostate cancer tissues 29, and EGR1‐deficient mice show impaired prostate tumorigenesis." (PMID 29427323, 2018). "An indication to such complexity as it pertains to EGR1 regulation and its downstream effects is highlighted by the fact that while it is thought to be a tumor suppressor in most malignancies, EGR1 seems to be surprisingly oncogenic in prostate cancer." (PMID 28081176, 2017). "In prostate cancer cell lines, EGR1 inhibition decreased cell growth, induced apoptosis, and decreased expression of the pro-inflammatory chemokine interleukin 8 (IL8) in a NF-κB-dependent pathway." (PMID 29228577, 2017). "The NF-κB binding site is reportedly important for EGR1-mediated IL-8 upregulation, and EGR1 knockdown inhibits IL-8 production and IL-8-mediated prostate cancer cell invasion." (PMID 28881635, 2017). "EGR1 levels are high in some prostate cancers, Wilm’s tumors, and melanoma cells bearing oncogenic B-RAF mutation compared to normal tissue." (PMID 29228577, 2017). "On the contrary, in pancreatic beta cells, glioma and colorectal cancer cells, prostate cancer, B-cell lymphoma and normal B cells EGR1 has anti-apoptotic or pro-proliferative role." (PMID 28081176, 2017). "EGR1 expression is elevated in prostate cancer and prostatic adenocarcinoma cell line and contributes to proliferation, cell survival and tumor progression." (PMID 29246166, 2017). "For example, in prostate cancer cells treated with a cinnamaldehyde derivative, the expression of Imp-7 and the transcription factor Egr1 are induced, and the Egr1 imported by Imp-7 activates apoptotic gene transcription." (PMID 28117667, 2017). "Another example is EGR-1 that has been shown to promote tumorigenesis of prostate cancer, whereas it also indicated the tumor-suppressive effect." (PMID 26910917, 2016). "EGR1 has been reported to be involved in the progression of prostate cancer and to increase invasion by ovarian cancer cells." (PMID 27835650, 2016). "Interestingly, Egr1 was markedly downregulated when cells were treated with metformin, and this could potentially be related with the recent discovery that metformin administration after prostate cancer diagnosis is associated with decreased mortality." (PMID 26548416, 2015). "For Egr1, it was revealed in the same study that it localizes to the mitotic spindle and microtubule meshwork in prostate cancer cell lines." (PMID 24722338, 2014). "In prostate tumors, Egr-1 expression is frequently upregulated, and Egr-1 expression in prostate cancer cells PC3 is mediated through an EGF-ERK-Elk-1 signaling cascade." (PMID 25004251, 2014). "Knockdown of EGR1 suppresses prostate cancer cell proliferation and tumor development in transgenic adenocarcinoma mouse prostate mice." (PMID 23945289, 2013). "The TRAMP and CR2-T-Ag mouse models of prostate cancer were utilized to further examine the functional role of Egr1 in the initiation and progression of the disease." (PMID 23342084, 2013). "Multiple investigators have reported the over-expression of Egr1 mRNA and protein in prostate cancer." (PMID 23342084, 2013).
prostate carcinoma (continued). "The levels of EGR1 increase with the degree of malignancy in prostate cancer, as indicated by the Gleason tumor score." (PMID 23029358, 2012). "Anti-hormonal therapy of prostate cancer becomes limited in the state of androgen-independent disease and Egr-1 seems also capable to govern prostate cancer progression under androgen resistance." (PMID 23202940, 2012). "Prostate cancer tissues also express high levels of p300, which leads to constitutively high levels of stable acetylated EGR1 protein, which is an important component in the transformation and progression of this disease." (PMID 23029358, 2012). "EGR1 is absent or expressed at low levels in normal prostate tissues; whereas the EGR1 promoter is regulated by a positive feedback loop between EGR1 and growth factors in prostate cancer cells, which results in constitutive growth." (PMID 23029358, 2012). "In a majority of human prostate carcinoma specimens Egr-1 protein expression control was lost, suggesting that high levels of Egr-1 plays a central role in the initiation of human prostate cancers." (PMID 23202940, 2012). "High levels of constitutive Egr-1 expression have been observed in most human prostate cancers and found to correlate with more advanced stages of malignancy and poor prognosis." (PMID 20087343, 2010). "Recently, transcription factors Sp1, Sp3 and Egr-1 have been identified as potent regulators of MT1-MMP expression in prostate cancer, endothelial and glomerular mesangial cells." (PMID 21176152, 2010). "KROX, also known as EGR-1, activates genes that are required for differentiation and mitogenesis, and is over-expressed in prostate cancer." (PMID 20946653, 2010). "In both bladder and prostate cancer Egr-1 is shown to regulate the expression of heparanase and hyaluronidase, which are implicated in the metastatic spread of cancer cells." (PMID 19878561, 2009). "SREBF1 gene has been shown as up-regulated in the prostate cancer and the early growth response 1 (EGR-1) is a transcription factor regulates the expression of its dependent genes involved in cell growth or survival." (PMID 20025723, 2009). "It has been suggested that Egr1 directly regulates genes that play a role in the development of prostate cancer." (PMID 19032775, 2008). "In human prostate cancer, EGR1 is over-expressed and in a mouse model of prostate cancer, EGR1 regulates genes essential for progression of tumor growth." (PMID 18631392, 2008). "M12 cells are metastatic prostate cancer cells and we observed high basal expression of Egr1 in these cells compared to several other prostate cancer cell lines." (PMID 19032775, 2008). "Prior treatment with siRNA to silence Egr1 expression in vivo reversed the expression of Egr1 target genes, clearly supporting the role of Egr1 as a functional transcription factor in M12 prostate cancer cells." (PMID 19032775, 2008). "We have shown that UV irradiation of prostate cancer cells leads to rapid and extensive induction of Egr1 via activation of the EGFR/ERK1/2 pathway and to apoptosis." (PMID 19032775, 2008). "Previous reports from our laboratory have shown that, under normal growth conditions, Egr1 is required for growth and proliferation of prostate cancer cells." (PMID 19032775, 2008). "Activation of the EGFR leads to rapid expression of Egr1 in a variety of settings, including prostate cancer cells." (PMID 19032775, 2008). "The qRT-PCR experiments were also done in the very widely used DU145 prostate cancer cell line, which also over-expresses Egr1 upon UV irradiation." (PMID 19032775, 2008). "In contrast, accumulating evidence based on in vitro studies, a survey of human surgical specimens, and transgenic mouse models indicate that Egr1 plays an important role in progression of prostate cancer." (PMID 19032775, 2008).
prostate carcinoma (continued). "We have shown that, upon UV stimulation, prostate cancer cells undergo Egr1-dependent apoptosis and this function of Egr1 is mediated by at least several of the newly identified target genes." (PMID 19032775, 2008). "Conversely, in the present study we observe that when prostate cancer cells are UV irradiated, Egr1 functions in inducing apoptosis of these cells." (PMID 19032775, 2008). "EGR1 plays a significant role in promoting the progression and metastasis of prostate cancer." (PMID 40996711, 2025). "Moreover, the expression level of EGR1 was lower in human prostate cancer tissue than in controls and still lower in higher Gleason grade prostate cancer than in lower Gleason grade prostate cancer." (PMID 40078339, 2025). "EGR1 has been shown to accelerate prostate cancer metastasis via the PI3K/PTEN/Akt pathway." (PMID 39866235, 2025). "EGR1 binds to the cyclin D2 promoter and regulates its expression in prostate cancer cell lines." (PMID 39501082, 2024). "In a mouse model of prostate cancers, it was observed that the administration of antisense oligonucleotides could inhibit the expression of Egr1 and ameliorate tumor growth." (PMID 38672136, 2024). "In prostate cancer, EGR1 could upregulate angiogenic and osteoclastogenic factors, including PDGFA, IL6, IL8, etc. and thus promote cancer metastasis." (PMID 36932397, 2023). "Similarly, the transcription factor Early growth response-1 (EGR-1) interacts with YAP to induce clonogenic cell death in prostate carcinoma cells." (PMID 36635265, 2023). "Moreover, the overexpression of HnRNP-L, a multifunctional RNA-binding protein, is involved in upregulating circCSPP1 to furtherly target EGR1 and lead to malignant development of prostate cancer." (PMID 37723588, 2023). "EGR1 has been reported to be involved in the proliferation of various stem cells and tumor cells, including hematopoietic stem cells, neural stem cells, gastric cancer cells, and prostate cancer cells." (PMID 37304127, 2023). "In prostate cancer, EGR1 also accelerated cancer metastasis PI3K/PTEN/Akt axis." (PMID 36932397, 2023). "In particular, high EGR1 levels were detected in prostate cancer." (PMID 36888606, 2023). "In addition, prostate cancer cells induced osteocytes to secrete GDF15 into the bone microenvironment which, in turn, stimulated early growth response 1 (EGR1) expression in prostate cancer cells and promoted tumor progression." (PMID 35994202, 2022). "Although YAP may be necessary for prostate cancer progression, it may have a contradictory role upon radiation, as it was reported to enhance apoptosis mediated by early growth response protein 1 (EGR-1)." (PMID 35954292, 2022). "Furthermore, EGR-1 has been described to act as a transcriptional repressor in melanoma cells and as an activator in breast, colon, and prostate cancer cells of the heparanase gene." (PMID 35409280, 2022). "For example, the high expression of EGR1 in prostate cancer is a potential precancerous event." (PMID 33842351, 2021). "Furthermore, another study also showed that EGR1 acts as a key regulator of prostate cancer through the suppression of GDF15." (PMID 34681812, 2021). "Cell migration, invasion, proliferation abilities, and autophagy activities were all gauged in prostate cancer cells to investigate whether EGR1 was targeted and regulated by miR-520h." (PMID 34760337, 2021). "Our study indicated that the increase in circCSPP1 in prostate cancer, which may be catalyzed by HnRNP-L, can induce cellular autophagy through the circCSPP1-miR-520h-EGR1 axis, leading to the progression of prostate tumor." (PMID 34760337, 2021). "Subsequently, to test whether EGR1 can rescue circCSPP1-induced progression and autophagy in prostate cancer cells, we first designed three siRNAs targeting EGR1, including si-365, si-749, and si-1878." (PMID 34760337, 2021).
prostate carcinoma (continued). "The level of the EGR1 protein in prostate cancer tissue positively correlates with the Gleason score, which predicts the tumor proliferation ability, and negatively correlates with the differentiation degree of prostate cancer cells." (PMID 33842351, 2021). "EGR1 has been reported to act as a tumour suppressor in several cancers, however, in prostate cancer, EGR1 has been proposed to be an oncogene, which may suggest a tissue specific biological function." (PMID 32518380, 2020). "However, we have presented firm evidence for the functional involvement of Egr-1 in increased hPar1 expression in prostate carcinoma." (PMID 30400241, 2018). "We conclude that TF, NF‐κB and EGR1 expression may be repressed by AR in prostate cancer patients, and that this signaling axis could also be active in human prostate epithelial cells in vivo." (PMID 29427323, 2018). "Although it is reportedly a tumor suppressor, new evidence suggests that EGR1 promotes prostate cancer progression, and might be an effective cancer therapy target." (PMID 28881635, 2017). "Indeed, EGR1 is overexpressed in certain cancers, such as prostate cancer, gastric cancer and cervical cancer." (PMID 28180113, 2017). "EGR1 can promote growth of some hormone regulated cancers including prostate cancer." (PMID 29228577, 2017). "The gene expression pattern of EGR1 suggests that it could potentially regulate a number of steps involved in the initiation and progression of prostate cancer, such as mitogenesis, invasiveness, angiogenesis, and metastasis." (PMID 26110651, 2015). "With the progress of high-throughput genomics and proteomics technology, increasing prostate cancer-related tumor markers, such as MIB-1/Ki67 labeling indices, DD3, EGR-1 and Bcl-2, are constantly being discovered and used in the diagnosis and prediction of prognosis of prostate cancer." (PMID 24959274, 2014). "The ability to reduce EGR1 expression may provide an efficient clinical treatment for prostate cancer, as downregulation of EGR1 may reduce growth factor induction and positive feedback to the EGF1 promoter." (PMID 23029358, 2012). "Repression of p19 by Egr1 was reported in prostate cancer cells." (PMID 21765927, 2011). "The mechanism behind Egr-1 expression in both bladder and prostate cancer are unexplored, but potent inducers of Egr-1 could be stimuli present in tumors in vivo such as hypoxia, growth factors and inflammation." (PMID 19878561, 2009). "Also inhibition of Egr-1 by antisense oligonucleotides reversed transformation of prostate cancer cells in vitro and in vivo." (PMID 19878561, 2009). "We examined the role of Egr1 in UV-irradiated tumorigenic human M12 prostate cancer cells." (PMID 19032775, 2008). "Both WT1 and EGR1 have been identified in prostate cancer cells, although their function in prostate epithelium is unknown." (PMID 18631392, 2008). "Our data clearly show that Egr1 is a mediator of transcription of numerous pro-apoptotic genes, which may work concordantly in UV-stimulated prostate cancer cells." (PMID 19032775, 2008). "EGR1 was shown to be overexpressed in prostate cancer and to be involved in the regulation of different steps involved in the initiation and progression of prostate cancer, including mitogenesis, invasiveness, angiogenesis, and metastasis." (PMID 11953881, 2002). "On the contrary, it was previously exhibited that EGR1 could form a complex with a Yes kinase-associated protein 1 (YAP1), thus regulating lipopolysaccharide-induced tissue factor expression in human endothelial cells or cell phenotypes of prostate cancer." (PMID 37188478, 2023). "Additionally, EGR1 has been identified in both the suppression and progression of tumors, with high expression of EGR1 being observed in several different cancers, such as glioma, lung, ovarian, and prostate cancer." (PMID 36765275, 2023).
prostate carcinoma (continued). "Therefore, we hypothesized that HnRNP-L regulates the circCSPP1-miR-520h-EGR1 axis to promote autophagy in prostate cancer cells, leading to tumor proliferation and metastasis." (PMID 34760337, 2021). "Finally, we demonstrated the potential competing endogenous RNA network, involving circCSPP1, miR-520h, and early growth response factor 1 (EGR1), in prostate cancer cells, which may play an important role in prostate cancer progression." (PMID 34760337, 2021). "Moreover, Egr1 selectively increases the activation of activation protein-1 (AP-1) and NF-κB, leading to the induction of proliferation and anchorage independence in prostate cancer cells." (PMID 31399076, 2019). "Notably, the largest gene class identified in the prostate carcinoma cell lines following EGR1 overexpression includes several neuroendocrine-related genes found highly expressed in the central nervous system, which pinpoints a direct control of neuron-specific genes by EGR1." (PMID 28321184, 2017). "However, in ovarian cancer, ALK+ lung adenocarcinoma, and prostate cancer, Egr-1 is oncogenic." (PMID 26136341, 2015). "Interestingly, Egr1 has been shown to act as an oncogene in prostate cancer." (PMID 23342084, 2013). "Previous work identified RRAD as an early growth response protein 1/2 (EGR1/2) target gene, and EGR expression levels are positively related to RRAD expression levels in prostate cancer." (PMID 36979412, 2023). "An example is in prostate cancer, where upregulated GCN5 downregulates Egr-1 expression via the PI3K/PTEN/Akt signaling pathway, negatively affecting IL-6-induced prostate cancer cell metastasis and epithelial-mesenchymal transition (EMT)." (PMID 34880761, 2021). "EGR1 and the lipogenic enzyme fatty acid synthase (FASN) are elevated in tissues adjacent to prostate cancer; this relationship is used as a predictive marker of recurrence." (PMID 29228577, 2017). "Among these six, HLF, JUN, c-MYC, EGR1, SMAD1, and HIF1A, were also identified as PTEN-controlled TFs, and four, ESR2, MYB, RELA, and USF1, as prostate cancer-related TFs." (PMID 22347425, 2012). "Evolutionary conserved transcription factor binding sites (TFBS) recognized by WT1, EGR1, SP1, SP2, AP2 and GATA1 were identified in the promoters of 24 differentially expressed prostate cancer genes from eight mammalian species." (PMID 18631392, 2008). "Analyses of the promoter regions of 11 genes expressed in prostate cancer epithelial cells showed that WT1 TFBS overlapped SP1 and EGR1 TFBS, either separately or together." (PMID 18631392, 2008). "Two of the TFs identified in the prostate cancer epithelial cells were the Wilms tumor gene (WT1) and the early growth response gene (EGR1), zinc finger transcription factors that bind at G-rich promoters of genes that regulate growth." (PMID 18631392, 2008). "Interestingly, simultaneous hypomethylation of its promoter, particularly at Early Growth Response 1 (EGR1) binding sites, combined with EGR1 upregulation, led to increased HPSE1 expression in prostate cancer." (PMID 40899692, 2025). "Furthermore, early growth response-1 (EGR1) plays a direct role in the regulation of angiogenesis and osteoclastogenic factors in prostate cancer bone metastasis." (PMID 38464516, 2024). "Early growth response‐1 (EGR1) downregulation in prostate cancer cells reduces both the number and size of metastases but does not affect tumour growth, suggesting that EGR1 regulates angiogenic factors and promotes metastasis." (PMID 39233332, 2024). "The results demonstrate that the EGR1 exhibited the highest mutation frequency followed by RRM2 and TPP1, while both SOCS2 and C11or54 do not show any mutations in prostate cancer samples." (PMID 35812443, 2022).